STAT3 (signal transducer and activator of transcription 3)
Diseases named in the same sentence as STAT3 in open-access papers (continued):
Sharing a sentence is not in itself a finding about the gene and the disease.
prostate carcinoma (continued). "Indeed, we found that similar to two other STAT3 blockers nimbolide and formononetin previously identified by our group in prostate cancer and multiple myeloma models respectively, OP-D could also cause a significant increase in ROS (H2O2 specifically)." (PMID 30413072, 2018). "In addition, CCL2/STAT3 has been shown to stimulate prostate cancer progression." (PMID 28157698, 2017). "An integrated network of Tgfb2, Il-6, Cxcl1, and Ctgf interactions revealed several putative binding partners in osteoblasts and/or prostate cancer and suggested that these secreted cytokines may control up-regulated transcription factors Junb, Cebpb and Stat3 in osteoblasts." (PMID 27600237, 2015). "Furthermore, STAT3 has been shown as a promising therapeutic target for prostate cancer." (PMID 24205155, 2013). "This study highlights the potential of SSA as a therapeutic agent for prostate cancer by identifying its key molecular targets (BCL2, ESR1, HIF1A, and STAT3) and validating its anti-proliferative and pro-apoptotic effects in PC3 cells." (PMID 39995416, 2025). "STAT3 is upregulated and activated in many human cancers, including NSCLC, prostate cancers, and melanomas." (PMID 39985075, 2025). "Neem-derived flavonoids and limonoids also inhibit STAT3, BCL-2, and enhance BAX, Caspase-3, and mitochondrial depolarization in hepatocellular and prostate cancers." (PMID 41346617, 2025). "Additional oncogenic cascades activated by Ang II include PAX2, STAT3, and JAK2 in prostate cancer and RAS/RAF/ERK1/2 in gastric malignancies." (PMID 40722848, 2025). "In DU145 prostate cancer cells, AST suppresses migration, proliferation, and STAT3 expression (protein/mRNA), while promoting apoptosis." (PMID 40565712, 2025). "Apelin-induced STAT3 activation was blocked by treatment with ERK, p38, and JNK inhibitors, indicating that apelin enhances integrin-dependent prostate cancer migration via the MAPK and STAT3 pathways." (PMID 40612675, 2025). "A crucial target is signal transducer and activator of transcription 3 (STAT3), which Cdk5 directly phosphorylates at Ser727 to enhance its transcriptional activity in prostate cancer and MTC." (PMID 41369365, 2025). "If induced by STAT3 and IL-6, CD46 expression protects cancer cells against complement lysis and fosters a pro-tumoral profile in breast and prostate cancers." (PMID 40370471, 2025). "First, network pharmacology was used to predict the potential targets of Osthole, identifying 68 targets shared with prostate cancer, including AKT1, TNF, IL6, STAT3, and CTNNB1." (PMID 40978029, 2025). "For instance, elevated miR‐375 promotes cell proliferation, invasion, and induces enzalutamide resistance in prostate cancer cells by targeting PTPN4, which in turn enhancing the phosphorylation of STAT3." (PMID 40145330, 2025). "In a phase I–II clinical trial, siltuximab treatment led to a reduction in active STAT3 and MAPK levels in prostate cancer patients." (PMID 40166646, 2025). "It promotes aggressive behavior in NSCLC and prostate cancer via activation of ERK/MYC and STAT3 signaling, respectively, while in medullary thyroid carcinoma, it correlates with nodal spread through YAP1 suppression." (PMID 40940980, 2025). "For example, Peng and colleagues reported that exosomes released from prostate cancer cells induced the polarization of TAMs to M2 TAMs by activating the AKT and STAT3 signaling pathways." (PMID 39889181, 2025). "Activation of STAT3 and inhibition of miR-8070 through the MAPK pathway are involved in apelin-induced prostate cancer migration." (PMID 40612675, 2025). "We have identified targets such as AKT1, TNF, IL6, STAT3, and CTNNB1 in Osthole’s inhibition of prostate cancer, along with pathways including the TNF signaling pathway, the Interleukin-6-17 (IL-6-17) signaling pathway, and the prolactin signaling pathway." (PMID 40978029, 2025).
prostate carcinoma (continued). "Interferon gamma (IFNγ), interferon alpha (IFNα), and interleukin 6 (IL6)-Janus kinase (JAK)-signal transducer and activator of transcription 3 (STAT3) signaling were assessed in enzalutamide-sensitive and -resistant prostate cancer cells." (PMID 41097714, 2025). "Through polymorphonuclear MDSC proliferation and activation mediated by LIF (an IL-6 type cytokine and STAT3 activator), TLR9 expression in prostate cancer cells facilitates immune evasion." (PMID 40727443, 2025). "In preclinical trials, ST3-Hel2A effectively inhibited the STAT3 NTD and blockaedSTAT3 dimerization in DU145 prostate cancer cell lines." (PMID 38339245, 2024). "In conclusion, this study provides a molecular basis for a novel role of genistein in simultaneously inhibiting the activation of STAT3 and other closely related oncogenic kinases, such as AKT, ERK, and p38, in prostate cancer DU145 cells." (PMID 39590337, 2024). "CCL5 produced by TAMs in prostate cancer enhances resistance to PTX and DOX via the STAT3/Nanog signaling pathway." (PMID 39199574, 2024). "In prostate cancer cells, the expression of SHMT2 is upregulated under the regulation of the typical JAK2/STAT3 pathway, affecting the early inflammatory response of cancer." (PMID 38594513, 2024). "The simultaneous silencing of STAT3 using shRNA and the overexpression of GRIM-19 synergistically increased the apoptosis of PC-3M prostate cancer cells." (PMID 38067351, 2023). "Recently, other SH2 domain inhibitors (323-1 and 323-2) have been developed and lead to the downregulation of STAT3 downstream genes, like the MCL1 apoptosis regulator (MCL1) and cyclin D1 (CCND1), in DU145 prostate cancer cells." (PMID 38067351, 2023). "While STAT3 pathway activation led to upregulation of CCL2 and induction of EMT in prostate cancer cells, CCL5 was also found to activate STAT3 signaling." (PMID 36836690, 2023). "TAM-secreted CCL5 promotes the self-renewal ability of PCSCs, and prostate cancer invasion, EMT, and metastasis by stimulating the β-catenin/STAT3 pathway." (PMID 37282627, 2023). "STAT3 phosphorylation and its nuclear expression level were decreased in GGCT-depleted A549 and prostate cancer PC3 cells." (PMID 37488242, 2023). "However, the molecular mechanisms responsible for the EHF-mediated inhibition of the STAT3 pathway in TNBC cells might be different from those in prostate cancer cells because the mRNA level of IL-6 was significantly increased by EHF overexpression in MDA-MB-453 cells." (PMID 37958443, 2023). "Research in prostate cancer cells demonstrates that leptin, by stimulating the STAT3 signaling pathway, promotes EMT and migration of prostate cancer cells." (PMID 37686525, 2023). "The increase in cell proliferation and chronic inflammation of the prostate activate the IL-6/STAT-3/cyclin D1 signaling pathway and play a significant role in the pathological progression of BPH and prostate cancer." (PMID 36601166, 2023). "TQ treatment has also decreased the phosphorylation of STAT3, which led to the inhibition of cell proliferation of PC3 human prostate cancer cells." (PMID 37375831, 2023). "Hypoxia-inducible miR-1181 is a known tumour suppressor in cancers such as pancreatic, ovarian and prostate cancer and is shown to target SOX2, STAT3 and HOXA10 to inhibit proliferation, migration and invasion and to promote EMT43–47." (PMID 35190587, 2022). "Our results reveal that the combined use of inhibitors directed against the IL6R/STAT-3 axis and TIGIT enhances the functional activity of NK cells against castration-resistant prostate cancer cells." (PMID 35465350, 2022).
prostate carcinoma (continued). "In turn, the upregulated CCL2 promotes STAT3 phosphorylation, leading to enhanced epithelial–mesenchymal transition (EMT) and metastasis of prostate cancer cells, thus promoting prostate cancer cell castration resistance." (PMID 36077785, 2022). "EA is also known to suppress the growth of prostate cancer cells and trigger the apoptosis of castration-resistant prostate cancer cells by attenuating the JAK2/STAT3/MCL-1 and NF-κB signaling pathways." (PMID 35242040, 2022). "We found that BM macrophages engulfing apoptotic prostate cancer cells promoted HIF-1α stability and subsequent HIF-1α and p-STAT3 nuclear translocation to induce the expression of the pro-inflammatory cytokine MIF." (PMID 36496973, 2022). "Inhibition of STAT3 eliminated activities of AKT and NF-κB, and STAT3/AKT/NF-κB was activated to repress cell apoptosis and promote cell proliferation of prostate cancer." (PMID 35543351, 2022). "In summary, this is the first proof of principle study that shows that miR-375 can facilitate prostate cancer progression and enzalutamide resistance via the PTPN4/STAT3 pathway." (PMID 36042375, 2022). "We first assessed the basal expression of the IL6R, STAT-3, and pSTAT-3 in 22Rv1, LNCaP, and DU145 prostate cancer cells." (PMID 35465350, 2022). "In line, STAT3 induces HIF-1α-mediated upregulation of miR-224, which is paralleled by reduced NKp46 expression and a dampened NK cell-mediated killing of prostate cancer cells." (PMID 35865518, 2022). "Furthermore, some studies have observed that expression of CD155 could be induced by pathways such as Raf-MEK-ERK-AP-1 and through the Sonic Hedgehog pathway, which is highly active in advanced prostate cancer and can be indirectly mediated by STAT-3 via regulation of the TTF-1 promoter." (PMID 35465350, 2022). "TLR9 expression in prostate cancer cells promotes immune evasion through LIF (an IL-6 type cytokine and STAT3 activator) mediated polymorphonuclear MDSC amplification and activation." (PMID 36365103, 2022). "In DU145 prostate cancer cells treated with EGF or IL-6, CuI (50 nM) was noted to reduce STAT3 activity and STAT3 nuclear localization." (PMID 36355554, 2022). "PKCε-mediated signal transducer and activator of transcription-3 (Stat3) Ser727 phosphorylation through integration with the MAPK cascade (RAF-1, MEK1/2, and ERK1/2) is essential for prostate cancer cell invasion." (PMID 36358843, 2022). "DIO-induced inflammation accelerated prostate cancer growth via IL6 secreted by prostatic macrophages, as well phosphorylated STAT3- (pSTAT3-) positive tumor cells." (PMID 35478937, 2022). "STAT3 is a member of the STAT family, which is fundamentally active among cancers such as breast, lung, gastric, and prostate cancers." (PMID 34513945, 2021). "In conclusion, STAT3 inhibition by GPB730 enhances the antitumoral activity of anti-CTLA-4 and decreases the intratumoral Treg frequency in a prostate cancer mouse model." (PMID 33786638, 2021). "Interestingly, we found that the MSC selected prostate cancer cells are also cross resistant to chemotherapies such as etoposide and docetaxel suggesting that STAT3 inhibition could be a viable route to resensitizing bone metastatic prostate cancer that is refractory to chemotherapy." (PMID 33526787, 2021). "In an earlier study, our group showed aggressive metastatic tumor growth in mice after deletion of signal transducer and activator of transcription 3 (STAT3) and phosphatase and tensin homolog (PTEN) in a murine transgenic mouse model for prostate cancer." (PMID 34885151, 2021). "Acacetin inhibits the translocation of STAT3 into the nucleus, resulting in selectively suppressed STAT3-activated cell proliferation and the induced apoptosis of DU145 prostate cancer cells." (PMID 34684783, 2021).
prostate carcinoma (continued). "The main drivers of prostate cancer progression, such as AR, PTEN/PI3K/AKT/mTOR, STAT3, NKX3.1 are influenced by PTMs, which changes their activity, expression, stability, and localization." (PMID 33572160, 2021). "We have previously shown that the STAT3 inhibitor galiellalactone inhibits cytokines such as GM-CSF and IL8 from prostate cancer cells and IL1ß, IL6 and IL10 secretion from monocytes." (PMID 33786638, 2021). "In summary, STING in tumor cells contributes to tumor rejection in prostate cancer cells, but its functions are frequently suppressed in tumor cells in part via JAK2 and STAT3 pathways." (PMID 33790360, 2021). "In parallel with current research, our previous studies confirmed the reduced proliferation of prostate cancer cells in the presence of HCA, which was attributable to decreased STAT3 phosphorylation." (PMID 33990689, 2021). "TQ has suppressed prostate cancer’s carcinogenesis at 45 μM by reducing IL-6 expression and inhibiting the phosphorylation of STAT3, AKT, and extracellular signal-regulated kinase (ERK) proteins in PC3 prostate cancer cells." (PMID 33923474, 2021). "For example, IL8 secreted from M2-polarized macrophages promotes prostate cancer progression via the STAT3/MALAT1 pathway, while knockdown of MALAT1 expression levels in prostate cancer cell lines inhibits cell proliferation, invasion and tumor formation." (PMID 34654454, 2021). "Our in vivo studies demonstrated that STAT3 inhibition with S3I-201, was effective in significantly reducing the growth of MSC-selected prostate cancer." (PMID 33526787, 2021). "In prostate cancer, sinomenine inactivates the phosphoinositide 3-kinase (PI3K)/Akt and Janus kinase (JAK)/signal transducer and activator of transcription 3 (STAT3) signal pathways, leading to the inhibition of cell viability, migration, and invasion." (PMID 33066509, 2020). "However, whether astaxanthin suppresses prostate cancer through STAT3 is yet to be elucidated." (PMID 32784629, 2020). "In a study of patients with prostate cancer, 1,25(OH)D was found to suppress many JAK-STAT signal components, including JAK1, STAT1, STAT2 and STAT3, which is consistent with our study." (PMID 32158346, 2020). "The STAT3 activation by β-caryophyllene oxide hindered proliferation, increased apoptosis, and blunted the invasive capability of DU145 prostate carcinoma cells." (PMID 32545187, 2020). "The complexes containing STAT3 and APE/Ref-1 bind to the promoter region of the vascular endothelial growth factor and increases its protein expression in pancreatic and prostate cancer." (PMID 33003453, 2020). "In prostate cancer, CD44 expression significantly correlates with IL-6, a STAT3-activating cytokine, and IL-6 or STAT3 inhibition both decrease CD44 and EMT-related protein levels in cancer cell lines." (PMID 33335857, 2020). "CT was identified as a potent STAT3 inhibitor that inhibited the phosphorylation of STAT3 Tyr705 and the target proteins such as survivin, Bcl-XL, and cyclin D1 through blocking the dimerization in DU145 prostate cancer cells." (PMID 32265690, 2020). "Polymorphonuclear myeloid-derived suppressor cells (PMN-MDSCs) in prostate cancer together with Arg1, NOS2 and STAT3 expression, exhibit a suppressive effect on T cell activity." (PMID 32488850, 2020). "Transcriptomic and proteomic analyses in prostate cancer (PCa) reveal high TCA/OXPHOS activity and low PDK4 expression in low STAT3 tumors." (PMID 32323921, 2020). "In preclinical trials, ST3-H2A2 was found toinhibit STAT-3 N-terminal domain, resulting in the blockage of STAT-3dimerization and apoptosis in prostate cancer cell lines." (PMID 32167126, 2020). "Herein, we used aggressive prostate cancer DU145 cells and found that astaxanthin inhibits their proliferation and suppresses the expression of STAT3." (PMID 32784629, 2020). "Collectively, up-regulated LINC00473 in prostate cancer facilitates cell proliferation and activates JAK/STAT3 signaling pathway." (PMID 32440687, 2020).
prostate carcinoma (continued). "As an oncogene, LIFR contributes to the subsequent activation of STAT3 and AKT pathways in prostate cancer, inducing the expression of a series of proliferation-related and transfer genes." (PMID 33505963, 2020). "The evaluation of prostate cancer tumor tissues with Gleason scores of 6 and 9 confirmed the trend in the expression levels of SHMT2 and PKM2, and the alternative phosphorylation of STAT3 already found in the two cell lines utilized in this study." (PMID 31500219, 2019). "When blocking IL-6 using antibody or STAT3 inhibition, the expression levels of CD44 and EMT-related proteins in prostate cancer cells were significantly attenuated both in vitro and in vivo." (PMID 31315262, 2019). "We only know, from one study of prostate cancer, that IL-6 stimulation leads to HSP27 phosphorylation and correlates with the EMT, suggesting the phosphorylated form is required for STAT3 activation." (PMID 31861612, 2019). "We previously reported that altered IL-6/STAT3 signaling is important for CRPC transition and aggressive behavior in prostate cancer." (PMID 31315262, 2019). "It was determined that the prostate cancer cells treated with the IIR cells or sensitized lymphocytes presented JAK2 and STAT3 phosphorylation." (PMID 30134795, 2018). "The studies about MDSCs in prostate cancer demonstrated that SOCS3 negatively regulated the development and function of MDSCs by inhibiting STAT3 activation." (PMID 30083161, 2018). "It was found that STAT3 and JAK2 were phosphorylated in both prostate cancer cell lines as a response to immune attack." (PMID 30134795, 2018). "Exogenous IL-6 leads to the production and secretion of IL-6 and PEc from prostate cancer cells and tumors, by activating IL-6R and JAK2/STAT3 pathway." (PMID 30134795, 2018). "Treatment of prostate cancer cells with ATR II (0, 50 and 100 μM) for 12 h inhibited the STAT3 and promoter activity reached up to 70 and 40% in DU145, whereas LNCaP was reached up to 60 and 12% compared to control." (PMID 30545141, 2018). "As recently demonstrated, CpG-STAT3siRNA conjugates used ex vivo eliminated STAT3-mediated ARG1 expression, thereby alleviating the tolerogenic effect of prostate cancer patients’ PMN-MDSCs on T cell proliferation and activity." (PMID 29921770, 2018). "Activated STAT3 promoted down-regulation of PCAT29 expression in both androgen dependent and independent prostate cancer cells by induction of miR-21." (PMID 28467474, 2017). "A strong correlation between both Hsp27 and EGF and advanced prostate cancer, as well as with EMT through IL-6/STAT3/Twist pathway, has been reported." (PMID 28430640, 2017). "Further we present evidence that altholactone results in induction of reactive oxygen species (ROS) generation in prostate cancer DU145 cells, followed by activation of Bax and suppression of STAT3 target gene products, including Bcl2, and survivin." (PMID 28178219, 2017). "During hypoxia, STAT3 and HIF-1α cooperatively activate HIF-1α target genes, VEGF, phosphoglycerate kinase 1 (PGK1), and carbonic anhydrase 9 (CA9) in prostate cancer cells." (PMID 28978186, 2017). "In prostate cancer EGF stimulates tumor progression via the coordinated ROS production, the phosphorylation of STAT3 (required for EGF-induced upregulation of HIF-1α) and the consequent induction of HIF-1α/Twist1/N-cadherin signaling pathway." (PMID 28430640, 2017). "In a similar trend to a known STAT3 inhibitor BP1-102, the lead compounds preferentially impaired viability in at least one of the STAT3-dependent breast or prostate cancer cell lines." (PMID 28636670, 2017). "A ZEB1-miR-375-YAP1 pathway was recently found to regulate epithelial plasticity in prostate cancer, while ZEB1 together with STAT3 were identified as key molecules altered at the early stages of prostate carcinogenesis." (PMID 28042859, 2016).